LASP1 (LIM and SH3 protein 1)
Diseases named in the same sentence as LASP1 in open-access papers (continued):
Sharing a sentence is not in itself a finding about the gene and the disease.
hepatocellular carcinoma (continued). "Furthermore, different molecular mechanisms were involved in the expression of vimentin mediated by LASP1 in HBX-positive hepatoma cells, and these findings may help us better understand the molecular mechanism of tumorigenesis mediated by HBX during HBV infection." (PMID 33722250, 2021). "Numerous human cancers, such as hepatocellular carcinoma (HCC), colorectal cancer (CRC), and prostate cancer have been shown to be affected by the oncogenic roles of the actin-binding LIM and SH3 domain protein 1 (LASP1)." (PMID 36619866, 2022). "Since then, several authors have studied LASP1 expression, at the mRNA or protein level, in different cancer types, reporting that its overexpression is inversely correlated with poor prognosis in breast and prostate cancer, medulloblastoma and hepatocellular carcinoma (HCC)." (PMID 36672776, 2022). "In the present study, we demonstrated that HBX could facilitate vimentin expression via LASP1 to promote EMT, proliferation, and migration of hepatoma cells." (PMID 33722250, 2021). "The suppression of vimentin has no significant role in LASP1 expression in HBX-positive hepatoma cells." (PMID 33722250, 2021). "We investigated whether LASP1 could enhance vimentin expression via the signal pathways and the results showed that over-expressed LASP1 could promote the activation of PI3-K, ERK, STAT3 pathways in hepatoma cells." (PMID 33722250, 2021). "In addition, the expression level of LASP-1 was significantly decreased in the HBx-expressing hepatoma cells after the treatment with LY294002, suggesting that PI3-K pathway is responsible for the upregulation of LASP-1 mediated by HBx in the hepatoma cells." (PMID 22897902, 2012). "Recent studies reported that miR-326 could directly control the expression of LIM and SH3 protein 1 (LASP1) to suppress cell proliferation and activate apoptosis in hepatocellular carcinoma (HCC)." (PMID 33376485, 2020). "Although the role of LASP-1 in hepatocarcinogenesis has been reported, the implication of LASP-1 interactors in HBV-related hepatocellular carcinoma (HCC) is not clearly evaluated." (PMID 28266596, 2017).
prostate carcinoma (19 papers, 2012 to 2025). A carcinoma that arises from epithelial cells of the prostate gland. "Also, the cytoskeleton associated genes EPPK1, a plakin family member, and the LIM and SH3 protein gene LASP1 fall in regions 8q24 and 17q12; the gains of both regions have been previously associated with prostate cancer progression." (PMID 23826159, 2013). "DANCR targeting miR-185-5p via FAK/PI3K/AKT/GSK3 β/snail pathway upregulates LIM and SH3 protein 1, thereby affecting cell migration and proliferation, promoting prostate cancer." (PMID 39668827, 2024). "Prostate cancer cells transfected with an miR-1-3p mimic downregulate the expression of the target gene LASP1, which reduces cell viability, invasion, and migration in prostate cancer." (PMID 39457531, 2024). "DANCR can also target miR-185-5p to increase expression of LIM and SH3 protein 1 promoting prostate cancer through the FAK/PI3K/AKT/GSK3β/snail axis." (PMID 37025585, 2023). "Additional experiments demonstrated that suppressing LASP1 with siRNA significantly hindered the proliferation and migration of prostate cancer cells, while overexpressing LASP1 had the opposite effect, promoting these processes." (PMID 38260135, 2023). "Reduced MMP1 levels after LASP1 depletion were also observed in LNCaP prostate cancer and T24 bladder cancer cell lines suggesting a general role of LASP1 in favoring distant metastasis by enhanced transcription and secretion of MMPs through invadopodia." (PMID 36497077, 2022). "LASP1 is highly expressed in various malignant tumors such as colon cancer and prostate cancer, and is closely related to tumorigenesis, invasion, and metastasis." (PMID 32812032, 2020). "In line with our results, miR-218-5p upregulation inhibited prostate cancer cell migration and invasion by directly regulating LASP1 expression." (PMID 31395079, 2019). "Reduced MMP1 levels after LASP1 depletion were also observed in LNCaP prostate cancer and T24 bladder cancer cell lines suggesting a general role of LASP1 in favoring distant metastasis by enhanced transcription and secretion of MMPs from invadopodia." (PMID 30298118, 2018). "LASP-1 is highly expressed in the central nervous system and contributes to the formation and progression of prostate cancer through a NF-KB pathway." (PMID 28651018, 2017). "Parallel studies discussed miR-218 to be involved in LASP1 overexpression, as miR-218 is downregulated in prostate cancer." (PMID 25622104, 2015). "In other cancer entities LASP1 is a promising marker as part of a marker set, like in prostate cancer." (PMID 25622104, 2015). "These bioinformatic predictions were confirmed in vitro as the inducible short hairpin RNA-mediated LASP1 knockdown impaired migration and proliferation in LNCaP prostate cancer cells." (PMID 24980827, 2014). "DANCR exerts its oncogenic effects via miR-185-5p/LASP1 axis in prostate cancer." (PMID 37025585, 2023). "The knock-down of LASP-1 by RNA interference resulted in a strong inhibition of the proliferation and migration of various cancer cells, such as breast, ovarian, colorectal and prostate cancer cell lines." (PMID 25760690, 2015). "Likewise, RNA interference with LASP1 reduced migration and proliferation of LNCaP prostate cancer cells and SW620 CRC cells." (PMID 25622104, 2015). "Finally in prostate cancer, LASP1 regulation at its 3′ UTR by miR-1 was demonstrated." (PMID 25622104, 2015). "In a related context, miR‐143‐3p was shown to inhibit EMT in prostate cancer by targeting AKT1 and to curb bone metastasis of Gleason 3+4 prostate cancer by targeting the LASP1‐mediated Wnt pathway." (PMID 40223182, 2025). "In prostate cancer, overexpression miR-203 controls proliferation, migration and invasion by directly targeting ZEB2, Bmi-1, survivin and LASP1." (PMID 29228583, 2017). "MiR-203 is often silenced in different malignancies, such as ESCC and prostate cancer, and its expression levels are inversely correlated with those of LASP1 in ESCC and prostate cancer." (PMID 25622104, 2015).
prostate carcinoma (continued). "Additionally, LASP1 is a target of the microRNA MIR-203, a gene known to control proliferation, migration, and invasive potential of prostate cancer cell lines." (PMID 23826159, 2013). "In addition, in prostate cancer, CKAP2, LASP1, BIRC5, WASF1, ASAP1 and RUNX2 mRNAs were recently identified as new miR-203 targets, suggesting that miR-203 could be a new prognostic marker and a therapeutic target in metastasis of prostate cancer." (PMID 23285092, 2012).
ovarian carcinoma (18 papers, 2007 to 2022). A malignant neoplasm originating from the surface ovarian epithelium. "14-3-3, found to be upregulated after LASP-1 depletion in ovarian cancer cells, has been implicated in cell cycle deregulation." (PMID 17211471, 2007). "Similar results concerning impaired proliferation and migration upon LASP1 knockdown were obtained with SKOV-3 ovarian cancer cell line." (PMID 25622104, 2015). "This was consistent with previous studies that implied LASP-1 is responsible for cellular proliferation due to cell-cycle arrest at the G2 phase in patients with breast and ovarian cancers." (PMID 24386158, 2013). "Our observations are consistent with earlier data showing a specific cell cycle arrest at G2/M and inhibition of cell proliferation after LASP-1 knockdown in breast and ovarian cancer cell lines." (PMID 20461080, 2010). "LASP-1 mediates cell migration, proliferation and survival in several mammary and ovarian carcinoma cell lines." (PMID 20419088, 2010). "Silencing of LASP-1 inhibits cell migration and proliferation by 40% in mammary and ovarian carcinoma cell lines." (PMID 20419088, 2010). "Silencing of LASP-1 by RNAi in highly LASP-1 expressing human breast and ovarian cancer cells led to reduced cell proliferation, migration and to cell cycle arrest in G2-phase." (PMID 17956604, 2007). "To investigate the function of LASP-1 in the ovarian cancer cell line SKOV-3, we performed a knock-down of the gene using the powerful RNAi technique." (PMID 17211471, 2007). "Silencing of the LASP-1 gene by RNA interference in the ovarian cancer cell line SKOV-3 reduced cell proliferation and cell migration in vitro without influencing the actin cytoskeleton, microtubule polymerisation and focal adhesion morphology." (PMID 17211471, 2007). "In this study we demonstrate that LASP-1 is highly overexpressed in ovarian cancer tissue and metastatic ovarian cancer cell lines." (PMID 17211471, 2007). "Moreover, overexpression of LASP-1 has been observed in a variety of malignant tumors such as metastatic breast cancer, ovarian cancer, bladder cancer, medulloblastoma, and hepatocellular carcinoma." (PMID 24386158, 2013). "The LASP-1 knock down ovarian carcinoma cells accumulate in the G2 phase of the cell cycle." (PMID 20419088, 2010). "LASP-1 expression has been reported to be increased in metastatic breast and ovarian cancer, suggesting that over-expression of LASP-1 may be involved in the migratory process of cancer cells." (PMID 18419822, 2008). "In order to study the significance of LASP-1 overexpression in ovarian cancer, we tested three ovarian cancer cell lines (SKOV-3, OAV-42 and PA-1) as well as two primary cell cultures derived from ascitic fluid of patients with peritoneal metastatic ovarian cancer for LASP-1 expression." (PMID 17211471, 2007). "In the present work, we analysed the effect of LASP-1 on biology and function of human ovarian cancer cell line SKOV-3 using small interfering RNA technique (siRNA).Transfection with LASP-1-specific siRNA resulted in a reduced protein level of LASP-1 in SKOV-3 cells." (PMID 17211471, 2007). "Meanwhile, our findings revealed that MRC2, LASP1, and ZNF839 were upregulated in ovarian cancers, especially in the subtype of serous ovarian cancer." (PMID 34336102, 2021). "Altogether, our findings demonstrated that LINC00909 is a ceRNA of MRC2, LASP1, and ZNF839 mRNA in the mediation of miR-23b-3p in ovarian cancer cells." (PMID 34336102, 2021). "We chose SKOV-3 cells as a cellular model for ovarian cancer because in these cells the BRCA1 and BRCA2 genes, which are located next to the LASP-1 gene on chromosome 17q21, are upregulated." (PMID 17211471, 2007). "Recently, LASP1 interaction with HER2 in ovarian cancer cells was demonstrated, however, no detailed domain binding analysis was performed but the authors claimed a LASP1 phosphorylation-independent association." (PMID 36497077, 2022).
ovarian carcinoma (continued). "The functional significance of LASP-1 in cancer metastasis is further supported by the presented data showing high LASP-1 expression in ovarian cancer tissue and reduced cell migration in ovarian cancer cells depleted of LASP-1." (PMID 17211471, 2007). "To assess the role of LASP-1 in ovarian cancer, we examined its expression in 26 ovarian cancer samples from different patients with or without invasive components." (PMID 17211471, 2007). "Interestingly, LASP1 gene has previously been reported to be overexpressed in CRC possessing a functional role in tumor metastasis and progression, and its overexpression in metastatic breast and ovarian cancer further supported this." (PMID 25104873, 2014). "Interestingly, the solid primary ovarian cancer tissue preparations of these two patients showed intensive LASP-1 staining (data not shown)." (PMID 17211471, 2007). "Overexpression of 14-3-3 led to cell cycle arrest in cell culture models and, therefore, might contribute to the observed G2 arrest in ovarian cancer cells lacking LASP-1." (PMID 17211471, 2007). "The absence of LASP-1 in cultures of primary ovarian cancer cells in contrast to established cell lines may reflect a downregulation of LASP-1 in the nonmigratory floating ascites cells which will be reverted after several passages of adherent cell culture." (PMID 17211471, 2007). "Only the three ovarian cancer cell lines showed a high LASP-1 signal, whereas the two primary cell lines were LASP-1 negative." (PMID 17211471, 2007).
nasopharyngeal carcinoma (13 papers, 2017 to 2025). A carcinoma arising from the nasopharyngeal epithelium. "This, in turn, promotes the formation of the MTDH–LASP1 complex, leading to the upregulation of LASP1 expression and ultimately promoting the growth and metastasis of nasopharyngeal carcinoma." (PMID 39759516, 2024). "By mediating the stability of diaphanous-related formin 1 antisense RNA 1 (DIAPH1-AS1) in an m6A-dependent manner, WTAP promotes the formation of MTDH-LASP1 complex and the expression of LASP1, facilitating the cell growth of nasopharyngeal carcinoma." (PMID 35804965, 2022). "Abnormal LASP1 expression has also been detected in several other cancer types, including prostate, pancreatic, ovarian, liver and nasopharyngeal cancers." (PMID 34862361, 2021). "Furthermore, lncRNA DIAPH1-AS1 acts as a molecular adapter to promote the formation of lncRNA MTDH-LASP1 complex and upregulate LIM and SH3 protein 1 (LASP1) expression, ultimately promoting the growth and metastasis of nasopharyngeal carcinoma cells." (PMID 36139062, 2022). "LASP1 was shown to be up-regulated in nasopharyngeal carcinoma." (PMID 35081873, 2022). "Second, LASP1, an actin-binding protein with roles in cytoskeletal organisation, was found to promote activation of the PI3K pathway and the progression of nasopharyngeal cancer (NPC) by promoting the ubiquitination-mediated degradation of PTEN53." (PMID 33659963, 2020). "LIM and SH3 protein 1 (LASP1) enhances tumor growth and metastasis in various cancers, but its role in nasopharyngeal carcinoma (NPC) remains unclear." (PMID 29531214, 2018).
pancreatic cancer (13 papers, 2019 to 2026). "In summary, we have identified the ANLN/EZH2/miR-218-5p/LASP1 signaling axis in pancreatic cancer cells, which provides new insights into the mechanism underlying pancreatic cancer progression and generates a mechanism-based novel framework for developing therapeutics in pancreatic cancer treatment." (PMID 31395079, 2019). "LASP1 upregulation partially reverses the tumor-suppressive effect of ANLN downregulation on pancreatic cancer cell progression." (PMID 38144520, 2023). "Anillin (ANLN) promoted the progression of pancreatic cancer through inducing EZH2 up-regulation by mediating the miR-218-5p/LASP1 signaling." (PMID 37604837, 2023). "ANLN contributes to pancreatic cancer progression by regulating the EZH2/miR-218-5p/LASP1 signaling axis." (PMID 38144520, 2023). "There is evidence for LASP1 upregulation in tumors under hypoxia as a hypoxia response element has been identified in the LASP1 promoter region and was shown to stimulate LASP1 expression in pancreatic cancer cells in vitro and in mouse tumor xenografts." (PMID 36497077, 2022). "It is reported that ANLN participates in the HMGA2-induced increase in the tumorigenicity of pancreatic cancer cells and through controlling the EZH2/miR-218-5p/LASP1 axis, ANLN deficiency dramatically reduces pancreatic tumor cell migration and invasion." (PMID 36199577, 2022). "In the present study, we showed that miR-218-5p upregulation repressed pancreatic cancer cell growth, migration and invasion by directly regulating LASP1." (PMID 31395079, 2019). "LASP1 upregulation partially reversed the tumor-suppressive effect of ANLN downregulation on pancreatic cancer cell progression." (PMID 31395079, 2019). "ANLN contributed to pancreatic cancer progression by regulating EZH2/miR-218-5p/LASP1 signaling axis." (PMID 31395079, 2019). "To further determine the role of LASP1 in the suppressive effects of miR-218-5p on pancreatic cancer progression, we rescued the expression of LASP1 by LASP1 overexpression plasmid vectors in the cells transfected with miR-218-5p." (PMID 31395079, 2019). "Further investigation showed that only LASP1 restoration partially reversed the effects of ANLN knockdown on pancreatic cancer cell proliferation, colony formation, cell migration and cell invasion." (PMID 31395079, 2019). "Collectively, these results demonstrated that ANLN promotes pancreatic cancer cell growth, migration and invasion by regulating miR-218-5p/LASP1 signaling axis." (PMID 31395079, 2019). "In this study, we showed that miR-218-5p upregulation inhibited pancreatic cancer cell growth, migration and invasion by directly regulating LASP1 expression." (PMID 31395079, 2019). "Further investigation showed that LASP1 restoration partially reversed the effects of ANLN knockdown on pancreatic cancer cell proliferation." (PMID 31395079, 2019). "EZH2 upregulation induced by ANLN promoted pancreatic cancer cell progression by miR-218-5p/LASP1 signaling axis." (PMID 31395079, 2019). "Likewise, the progression of pancreatic cancer was influenced by ANLN through the miR-218-5p/LASP1 signaling pathway, which is mediated by EZH2." (PMID 41513610, 2026). "Although previous reports and our results suggest that LASP1 contributes to pancreatic cancer cell growth and metastasis, the downstream mechanisms of LASP1 remains unclear in pancreatic cancer." (PMID 31395079, 2019). "In addition, the CCK-8 and colony formation assays indicated that the suppressive effects of ANLN knockdown on pancreatic cancer cell growth were restored by LASP1 re-expression." (PMID 31395079, 2019). "In addition, CCK-8 analysis and colony formation assay revealed that the suppressive effects of miR-218-5p upregulation in pancreatic cancer cell growth were partially restored by LASP1 re-expression." (PMID 31395079, 2019). "Taken together, EZH2 induced by ANLN may promote pancreatic cancer progression by regulating miR-218-5p/LASP1 signaling axis." (PMID 31395079, 2019).